RBP4 (retinol binding protein 4)
Diseases named in the same sentence as RBP4 in open-access papers (continued):
Sharing a sentence is not in itself a finding about the gene and the disease.
chronic kidney disease (continued). "Relationship between baseline glomerular filtration rate stratified by chronic kidney disease (CKD) stage and urinary retinol binding protein 4/creatinine ratio (uRBPCR), urinary protein creatinine ratio (uPCR), urinary albumin/creatinine ratio (uACR) and fractional excretion of phosphate." (PMID 34374069, 2021). "The authors suggested that these C-terminally truncated RBP4 proteins are generated in hepatocytes and, after its release, are rapidly cleared by the kidney in healthy individuals, but not in patients with chronic renal failure." (PMID 33790810, 2021). "For example, plasma RBP4 levels tended to decrease concomitantly with increased necroinflammatory activity, NAFLD activity score, and fibrosis score in NAFLD patients, but increase during chronic kidney disease." (PMID 33135589, 2020). "Importantly, dysfunctions of both, the liver and kidneys, are known to influence RBP4 homeostasis: chronic kidney diseases (CKD) and chronic liver diseases (CLD) interfere with RBP4 metabolism through their action on RBP4 synthesis and catabolism." (PMID 18752671, 2008). "Not unexpectedly, chronic kidney disease (CKD) can also increase RBP4 in the circulation." (PMID 35334893, 2022).
coronary artery disease (28 papers, 2013 to 2025). "In conclusion, RBP4 involved in the pathophysiological process of coronary heart disease, as a risk factor, has shown valuable in predictor of coronary complexity and the occurrence of adverse cardiovascular events in patients with CAD." (PMID 35309061, 2022). "But in a 16-year prospective case-control study, both full-length and total RBP4 levels were found to be strongly associated with the risk of coronary heart disease in women, with this association diminishing over time." (PMID 35309061, 2022). "We did not detect a significant association between higher genetically predicted RBP4 levels and stroke or coronary heart disease." (PMID 36017698, 2022). "RBP4 is expected to be a new biological indicator of coronary heart disease, and a clinical risk factor of coronary heart disease." (PMID 35309061, 2022). "RBP4 gene polymorphism was also found to be closely associated with coronary artery disease." (PMID 35309061, 2022). "This study aims to determine if genetic polymorphisms in RBP4 are associated with the risk of coronary artery disease (CAD) in Chinese patients." (PMID 25479076, 2014). "Previous studies have revealed that RBP4 is closely correlated with atherosclerosis, coronary disease and earlier CVD." (PMID 24932224, 2014). "Therefore, we aimed to evaluate the relationship between RBP4 with the presence and severity of coronary artery disease (CAD) in this study." (PMID 34616228, 2021). "Similarly, serum levels of RBP4 were elevated in patients with coronary artery disease." (PMID 36304097, 2022). "Retinol binding protein 4 (RBP4) has been proposed to play a role in the pathophysiology of coronary artery disease (CAD), but previous findings on the association of RBP4 levels with CAD are inconsistent." (PMID 34419052, 2021). "RBP4 expression is increased upon liver injury, NASH (as a sensitive maker of NASH), or coronary heart disease (especially with acute coronary syndrome [ACS]) and thus, has been proposed to be a new risk factor for coronary heart disease." (PMID 26631018, 2015). "The interplay between the novel adipokine retinol-binding protein-4 (RBP4) and coronary artery disease (CAD) is still obscure." (PMID 25142320, 2014). "The finding of the present study is in line with that of who observed elevated RBP-4 in patients with overt hypothyroidism, but without coronary heart disease." (PMID 33133591, 2020). "The predictive role of retinol-binding protein 4 (RBP4) in the adverse prognosis of patients with stable coronary artery disease (CAD) has not been well-defined." (PMID 35369314, 2022). "In patients with coronary artery disease (CAD), RBP4 levels are significantly higher than in those without CAD and positively correlate with the number of affected vessels." (PMID 41303567, 2025).
Hepatic steatosis (25 papers, 2008 to 2025). Steatosis is a term used to denote lipid accumulation within hepatocytes. "Retinol-binding protein 4 (Rbp4) is a key regulator of lipid metabolism, and its abnormal expression is closely related to hepatic steatosis." (PMID 40442809, 2025). "Secondly, the lipid-lowering activity stems from Rbp4 downregulation, which significantly ameliorates hepatic steatosis by reducing lipid droplet accumulation in hepatocytes." (PMID 40442809, 2025). "Consistent with this, a high-fat diet aggravated RBP4-induced hepatic steatosis in these mice, indicating RBP4 stimulation of adipose tissue lipolysis and fatty acid release." (PMID 38673873, 2024). "Of note, recently, novel RBP4 antagonists were reported to reduce hepatic steatosis in transgenic mice with adipocyte-specific overexpression of RBP4." (PMID 36009862, 2022). "The study using RBP4 transgenic mice also demonstrated that RBP4 stimulated hepatic mitochondrial dysfunction and induced hepatic steatosis." (PMID 34944728, 2021). "Moreover, adipocyte-specific RBP4 overexpression in transgenic mice has been shown to induce hepatic steatosis and glucose intolerance while increasing inflammatory markers." (PMID 41157128, 2025). "Indeed, lower serum adiponectin and resistin concentrations and higher serum RBP4 concentrations were evident in children with advanced liver steatosis." (PMID 32718097, 2020). "Moreover, according to a recent study, RBP4 induces hepatic steatosis because it activates primary inflammatory effects in adipose tissue and stimulates proinflammatory cytokines, such as TNF-α, while the suppression of RBP4 prevented NAFLD in mice models." (PMID 30096951, 2018). "In addition, the same authors indicated that adiponectin, resistin and RBP4 levels could be useful for differentiating patients with advanced liver steatosis from those with mild steatosis." (PMID 32718097, 2020). "Our previous work in adolescents with hepatic steatosis also detected EV-derived proteins involved in complement activation and lipid metabolism, several of which exhibit high hepatic expression (e.g., FGL1, RBP4, GC)." (PMID 41354933, 2025). "Our results showed that RBP4, in addition to being elevated in subjects with MASLD compared to the control group, could predict hepatic steatosis and hepatic fat content with a moderate capacity." (PMID 39138826, 2025). "The HCV core transgenic mice exhibited nonobese hepatic steatosis, had higher hepatic RBP4 expression, higher serum levels of RBP4 and triglycerides, but comparable HOMA-IR levels than non-transgenic littermates." (PMID 33135589, 2020). "Interestingly, adipose tissue-specific overexpression of human RBP4 triggers hepatic steatosis and glucose intolerance despite the absence of alteration sin retinoid concentrations." (PMID 38673873, 2024). "Although RBP4 expression in adipose tissue has been shown to induce hepatic steatosis by promoting lipolytic pathways, RBP4 expression in the liver is not so closely related to fat accumulation itself and is more involved in the synthesis of the retinoid complex." (PMID 36674839, 2023). "In parallel, the impact of HCV core on RBP4 expression was assessed by using the tetracycline (tet)-off conditional HCV core transgenic mice with nonobese hepatic steatosis and hypolipidemia, both phenotypes mimicked HCV-associated metabolic alterations in the human." (PMID 33135589, 2020). "Likelihood of fatty liver, expressed as FLI > 60, did not correlate with RBP4 levels." (PMID 29524177, 2018).
non-alcoholic fatty liver disease (24 papers, 2008 to 2026). "Previous reports on the association between retinol binding protein 4 (RBP4) and nonalcoholic fatty liver disease (NAFLD) were controversial." (PMID 28332619, 2017). "Similar inverse correlations between RBP4 levels and the severity of hepatic damage or fibrosis have also been observed in non-alcoholic fatty liver disease." (PMID 39589965, 2024). "Retinol binding protein (RBP) and especially RBP4 have been shown to play a role in glucose homeostasis in the liver in various pathological processes such as non-alcoholic fatty liver disease." (PMID 36851123, 2023). "It was shown that RBP4 expression was aberrantly elevated in non-alcoholic fatty liver disease (NAFLD) in middle-age human and animal models, as well as positively associated with hepatic mitochondrial dysfunction combined with increased hepatic triglyceride accumulation." (PMID 29524177, 2018). "However, whether nonalcoholic fatty liver disease (NAFLD) is related to RBP4 is unclear." (PMID 36670387, 2023). "And they got a negative conclusion about relationship of RBP4 and nonalcoholic fatty liver disease, and RBP4 decreased along with the deterioration of liver lesions." (PMID 25890223, 2015). "We investigated the relationship between non-alcoholic fatty liver disease (NAFLD) and serum RBP4 in nondiabetic adults." (PMID 17941908, 2008).
endothelial dysfunction (23 papers, 2008 to 2025). In vascular diseases, endothelial dysfunction is a systemic pathological state of the endothelium (the inner lining of blood vessels) and can be broadly defined as an imbalance between vasodilating and vasoconstricting substances produced by (or acting on) the endothelium. "We identified a positive correlation of RBP4 with systolic blood pressure, which predisposes to endothelial dysfunction as well." (PMID 36561568, 2022). "The alterations in RBP4 metabolism during CKD are of interest in relation to T2DM since T2DM patients are exposed to increased oxidative stress which has been reported to be linked to endothelial dysfunction." (PMID 18752671, 2008). "In addition, the association between high mean corpuscular volume and low RBP4 levels with all-cause mortality in hemodialysis patients likely involves complex interactions among anemia, inflammation, oxidative stress, endothelial dysfunction, and disrupted vitamin A metabolism." (PMID 40881125, 2025). "On the one hand, weight gain can lead to increased release of adipokines (e.g., leptin, tumor necrosis factor alpha, retinol-binding protein 4) and cytokines from adipose tissue, leading to inflammatory endothelial dysfunction and metabolic dysfunction." (PMID 41357077, 2025). "The authors observed significantly higher levels of low-molecular-weight proteins (including RBP4) in the urine of normoalbuminuric T2DM patients with endothelial dysfunction compared with T2DM subjects with normal endothelial function and healthy controls." (PMID 36011513, 2022). "Recently, RBP4 has been identified as a leading factor for endothelial dysfunction, a landmark pathology observed in preeclampsia as well as in GDM." (PMID 36558360, 2022). "In this context, retinol-binding protein 4 (RBP4)—an adipokine primarily secreted by adipocytes and hepatocytes and involved in transporting retinol in blood—has been associated with endothelial dysfunction, cardiovascular disease and periodontitis." (PMID 32635585, 2020). "The inverse relation between RBP4 and flow-mediated vasodilatation (flow-mediated dilation) endothelial dysfunction are evident in normotensive individuals and in diabetic patients." (PMID 30038059, 2018). "Given their possible involvement in key molecular pathways—ranging from oxidative stress and low-grade inflammation to endothelial dysfunction, altered mineral metabolism and tissue remodeling—RBP4, LCN2, ApoM, Klotho and MGP represent more than isolated biomarkers." (PMID 41303567, 2025). "In addition, increased RBP4 promotes renal and vascular inflammation via activation of pro-inflammatory pathways, endothelial dysfunction and oxidative stress described before, all of which contribute to the progression of CKD in the context of CKM syndrome." (PMID 41303567, 2025). "The elevated RBP-4 signifies the progression of IR and endothelial dysfunction." (PMID 34571734, 2021). "Because of both disorders sharing the same hypothesized mechanisms leading to endothelial dysfunction, and, thus, inflammation, RBP-4 can be the typical cytokine of IR and the severity of CAD in patients with T2D." (PMID 34571734, 2021). "Inflammation and consequent endothelial dysfunction induced by stimulation of the expression of pro-inflammatory molecules, such as TGF-beta, by RBP4 may also be involved in metastasis formation." (PMID 41007818, 2025). "Quite surprisingly, in healthy normotensive subjects RBP4, but not E-selectin, was significantly related to FMD and MDA, suggesting a specific role for this adipokine in marking endothelial dysfunction and oxidative stress, but not endothelial activation." (PMID 22938533, 2012).
ovarian carcinoma (22 papers, 2013 to 2025). A malignant neoplasm originating from the surface ovarian epithelium. "Our results suggested that RBP4 is a potential biomarker for diagnostic of screening ovarian cancer." (PMID 25250314, 2014). "The association between RBP4 and tumor size suggests that RBP4 may promote tumor growth, as also described in ovarian cancer, where RBP4 enhances migration and proliferation by activating RhoA/Rock1 and ERK pathways and upregulating MMP2 and MMP9." (PMID 41007818, 2025). "Considering RBP4 as a circulating protein, targeting RBP4 could be a relative easy option for ovarian cancer treatment, especially those associated with obesities." (PMID 29642915, 2018). "In addition, epidemiological study showed that higher circulating levels of RBP4 are associated with colon adenoma, ovarian cancer and oral squamous cell cancer." (PMID 28002423, 2016). "The RBP4/RhoA/Rock1 axis has been found to regulate the proliferation, migration, and invasion of ovarian cancer cells, while NRG2 was identified as a prognostic marker for GC and breast cancer and LBP as a prognostic marker for GC." (PMID 40406134, 2025). "In ovarian cancer, RBP4 overexpression stimulates the expression of MMP-2 and MMP-9, which increases the migration of tumor cells and affects the unfavorable prognosis." (PMID 41007818, 2025). "Studies have found that the overexpression of RBP4 in ovarian cancer cells promotes the proliferation and migration of cancer cells." (PMID 39518840, 2024). "There is increasing evidence that RBP4 is associated with cancer development; for example, high levels of RBP4 promote the migration and proliferation of ovarian cancer cells through stimulation of MMP2 and MMP9 expression." (PMID 37313408, 2023). "Available studies have shown that RBP4 is highly associated with ovarian diseases such as PCOS, human ovarian cancer and porcine ovarian cysts." (PMID 35883591, 2022). "Our data was consistent with the reported functions of RBP4 in prostate cancer cells and ovarian cancer cells." (PMID 36632438, 2022). "RBP4 can drive ovarian cancer cell migration and proliferation through RhoA/Rock1 and extracellular signal-regulated kinase pathways, which are involved in the expression of matrix metalloproteinase (MMP) 2 and MMP9." (PMID 35883591, 2022). "On the other hand, the serum concentration of RBP4 in ovarian cancer patients was significantly lower than that in healthy volunteers, according to mass spectrometry data." (PMID 36632438, 2022). "For example, immunohistochemistry results demonstrated that RBP4-protein expression levels in ovarian cancer tissues were higher than those in normal ovarian tissue and exerted prognostic predictive roles." (PMID 36632438, 2022). "RBP4 is highly expressed in ovarian cancer cells as well and a high level of RBP4 has been documented the serum samples from patients with ovarian cancer." (PMID 34072419, 2021). "It has been demonstrated that the serum levels of RBP4 are elevated in patients with ovarian cancer, and the expression of RBP4 is increased by approximately four-fold in ovarian cancer tissues compared with its expression in the benign ovarian tissues." (PMID 34072419, 2021). "The overexpression of RBP4 leads to the increased migration and proliferation of ovarian cancer cells via the induction of MMP 2/9, which is inhibited by RBP4 knockdown." (PMID 34072419, 2021). "Other authors have shown that knockdown of RBP4 significantly reduces ovarian cancer cell migration and proliferation driven through the RhoA/Rock1 and extracellular signal-regulated kinase (ERK) pathways." (PMID 32156052, 2020). "The overexpression of RBP4 resulted in cancer cell migration, and RBP4 was upregulated in ovarian cancer cells." (PMID 31212896, 2019). "RBP4 can drive ovarian cancer cell migration and proliferation through RhoA/Rock1 and extracellular signal-regulated kinase pathways involving matrix metalloproteinase (MMP) 2 and MMP9 expressions." (PMID 31412686, 2019).